ANP32D (acidic nuclear phosphoprotein 32 family member D)
Synonyms: PP32R2
Tractability: No criterion of Open Targets' tractability assessment is met for any kind of drug.
Gene: Protein-coding gene on chromosome 12 (48,472,559 to 48,473,622, forward strand). Ensembl gene ENSG00000139223.
Subcellular location (Human Protein Atlas): Nucleoplasm; Centrosome
Genetic constraint (gnomAD): Loss-of-function variants: 6 observed, 8.19 expected, observed/expected ratio (o/e) 0.73, 90% interval 0.4 to 1.43. That is too few expected variants to judge how well the gene tolerates losing a copy. Missense variants: 163 observed, 154.44 expected, observed/expected ratio (o/e) 1.06, 90% interval 0.93 to 1.2. Synonymous variants: 69 observed, 62.75 expected, observed/expected ratio (o/e) 1.1, 90% interval 0.9 to 1.34.
Homologues: Orthologues: dog ANP32A (85% identical), mouse Anp32a (85% identical), zebrafish anp32a (84% identical), chimpanzee ANP32D (83% identical), tropical clawed frog anp32a (81% identical), rat Anp32a (79% identical), Drosophila melanogaster Mapmodulin (52% identical), Caenorhabditis elegans F33H2.3 (38% identical), Caenorhabditis elegans T19H12.2 (36% identical). Paralogues in human: ANP32A (89% identical), ANP32B (71% identical), ANP32E (66% identical).
Diseases named in the same sentence as ANP32D in open-access papers:
ANP32D is named in the same sentence as 1 disease in open-access papers, as found by Europe PMC text mining. Sharing a sentence is not in itself a finding about the gene and the disease.
ANP32D shares sentences with these, for which no sentence is quoted: chronic mountain sickness (1 paper).